AR (androgen receptor)
Diseases named in the same sentence as AR in open-access papers (continued):
Sharing a sentence is not in itself a finding about the gene and the disease.
prostate carcinoma (continued). "Androgen/AR signaling is widely recognized as a critical driver of hormone-related malignancies, particularly prostate cancer in which AR activation is a key oncogenic driver, and androgen deprivation therapy (ADT) remains a cornerstone of treatment." (PMID 41486951, 2026). "Prostate cancer, one of the most prevalent cancers worldwide, is heavily dependent on the activation of the androgen receptor (AR) signaling pathway during its initiation and progression." (PMID 41492471, 2026). "The precision and lineage-selective action of DALTAC-1 highlight its strong translational potential for treating AR-driven prostate cancer." (PMID 42094447, 2026). "Neuroendocrine Prostate Cancer (NEPC) is a rare and clinically aggressive subtype of Prostate Cancer (PCa) with its own biological behavior, unfavorable prognosis, and resistance to androgen receptor (AR) directed therapies." (PMID 41689691, 2026). "Androgen deprivation therapies targeting the androgen receptor (AR) signaling pathway are the primary treatment strategy for prostate cancer." (PMID 41492471, 2026). "Collectively, these findings highlight compound 18ad as a promising lead scaffold for the development of targeted AR therapies for prostate cancer management." (PMID 41993879, 2026). "Androgen-deprivation therapy for prostate cancer, using anti-androgenetic drugs such as flutamide or bicalutamide, as well as castration, can lead to AR up-regulation or amplification and hypersensitization." (PMID 41596366, 2026). "This process promotes prostate cancer progression and resistance to androgen receptor signaling inhibitors (ARSis)." (PMID 41605902, 2026). "Human clinical models of prostate cancer validate that AR negatively regulates COUP‐TF1 at both the mRNA and protein levels." (PMID 40948103, 2026). "While AR-mediated transcription is required for male sexual differentiation, aberrant androgen-driven AR activity is a crucial driver of prostate cancer (PCa) formation and progression." (PMID 41602415, 2026). "In contrast to these reports, we identify a previously uncharacterized activity of the AR that suppressed anticancer immunity by limiting the innate immune response in prostate cancer cells." (PMID 41542764, 2026). "Here, we demonstrate that androgen receptor pathway inhibitor (ARPI) plus irradiation (IR) triggered robust anticancer immunity in prostate cancers in both patients and mice." (PMID 41542764, 2026). "In prostate cancer cells, AR is produced in the cytoplasm and translocated to the nucleus upon androgen binding." (PMID 41247636, 2025). "The increased availability of next generation sequencing and the advent of liquid biopsy has led to several publications outlining evolution of AR alterations during the course of prostate cancer treatment." (PMID 38383885, 2025). "Antiandrogens such as ET516 can disrupt AR condensates by inhibiting AR phase separation, effectively suppress AR transcriptional activity and inhibits the tumor growth of prostate cancer cells expressing AR‐resistant mutants." (PMID 40599234, 2025). "Taken together, these data illustrate that NKX3.1 is necessary and sufficient for the survival of prostate cancer cells, thereby solidifying its oncogenic role in these late-stage and AR-targeted therapy-resistant models of disease." (PMID 39858088, 2025). "Enzalutamide is a novel androgen receptor inhibitor used for castration-resistant prostate cancer treatment." (PMID 40417209, 2025). "PRPF8 interacts with the androgen receptor, regulating its function in prostate cancer cells and controlling its transcriptional activity." (PMID 40136404, 2025). "AR is the most critical transcription factor in prostate cancer, but other dysregulated pathways also exist, such as the MTA1/PTEN/AKT pathway." (PMID 40023399, 2025).
prostate carcinoma (continued). "Recent study suggests that AR signaling promotes prostate cancer cell growth by increasing G6PD expression and enhancing flux through pentose phosphate pathway via activation of the mTOR-SREBP1 axis." (PMID 41514554, 2025). "Lastly, these agents can also decrease the transcriptional activity of the androgen receptor, which, ultimately, is the main way the androgen receptor employs its carcinogenic activities in prostate cancer." (PMID 40647555, 2025). "Subsequent investigations revealed its ability to induce ROS-mediated autophagy and apoptosis in androgen receptor (AR)-positive prostate cancer cells." (PMID 41154606, 2025). "One of the most significant challenges in treating prostate cancer is the emergence of resistance to androgen receptor (AR)-targeted therapies." (PMID 40034825, 2025). "In contrast, androgens are well-known drivers of prostate cancer, where androgen receptor (AR) signaling promotes tumor progression." (PMID 39726664, 2025). "Of specific relevance to prostate carcinoma, the AR plays a central role for the survival and growth of prostate carcinoma and consequently has served as a key target for therapeutic intervention." (PMID 40956611, 2025). "The pathophysiology of prostate cancer underscores the significance of androgen receptor (AR) activation and AR-driven transcriptional programs, making androgen deprivation therapy (ADT) and androgen-receptor targeted therapy (ART) essential treatments." (PMID 40542015, 2025). "In oncology, GR antagonists are being investigated in prostate cancer, where GR signaling can bypass androgen receptor (AR) inhibition, contributing to therapy resistance." (PMID 40595974, 2025). "Enzalutamide (ENZ), a second-generation androgen receptor inhibitor, was developed to treat castration-resistant prostate cancer." (PMID 40154619, 2025). "Our findings - including the significant association with AR expression - are also in agreement with functional evidence for androgenic regulation of MTAP expression and a role of MTAP for prostate cancer cell growth." (PMID 40554389, 2025). "In this review, we focus on the roles of transcriptional CDKs in prostate cancer growth, metastasis and therapy resistance and discuss their interplay with AR, MYC and BRD4." (PMID 40163908, 2025). "Androgen-targeted therapies (ATTs) constitute the primary treatment options for metastatic prostate cancer, and they are most effective in well-differentiated prostate cancer cells with high AR activity." (PMID 40511682, 2025). "Advanced prostate cancer is treated by targeting the androgen receptor (AR) pathway but eventually develops resistance to castration." (PMID 40969255, 2025). "Beyond its methyltransferase activity, EZH2 can directly bind to the androgen receptor (AR) promoter, activating gene transcription and contributing to prostate cancer (PCa) progression." (PMID 40761481, 2025). "Crona D.J., Whang Y.E. Androgen receptor-dependent and -independentmechanisms involved in prostate cancer therapy resistance.Cancers (Basel)." (PMID 41164275, 2025). "For instance, it reverses docetaxel resistance in prostate cancer through the androgen receptor and PI3K/Akt signaling pathway, and reverses multi‐drug resistance in hepatocellular carcinoma cells through the FZD7/β‐catenin pathway." (PMID 41368332, 2025). "IHC assessed key prostate cancer markers (AR, AMACR, KLK3, PTEN, NKX3-1, VIM), while WES compared somatic alterations in PGCA, adjacent adenocarcinoma, and stromal tissue." (PMID 40873563, 2025). "In this way, a positive feedback loop is formed between NSUN2 and AR to promote the progression of prostate cancer." (PMID 41413017, 2025). "In recent years, with continuous advancements in medical technology, novel endocrine therapies—particularly second-generation androgen receptor (AR) antagonists—have provided new treatment options for patients with advanced prostate cancer." (PMID 41179800, 2025).
prostate carcinoma (continued). "Alternatively small molecules targeting the RBP NONO have been developed to relocate and trap this RBP in nuclear foci by stabilizing protein-RNA interaction, effectively reducing the expression of the androgen receptor in prostate cancer cells." (PMID 40691806, 2025). "This study reveals that HIC1 inhibits the progression of prostate cancer by regulating the AR/IRS2 axis, thus addressing a research gap and enhancing our understanding of HIC1's mechanism of action." (PMID 41050263, 2025). "Despite the development of multiple new treatments for advanced prostate cancer, treatment resistance in the clinic is inevitable and commonly driven by the reactivation of AR signaling." (PMID 39787247, 2025). "The growth and survival of prostate cancer depends on the steroid nuclear receptor termed androgen receptor (AR)." (PMID 39948708, 2025). "Over the past decade, however, a deeper understanding of prostate cancer biology and the androgen receptor (AR) axis has driven a remarkable transformation in the therapeutic strategies used to treat advanced disease." (PMID 40542935, 2025). "In cancer, high-level AR expression commonly occurs in prostate cancer, but many other tumor entities can also express significant levels of AR." (PMID 41463239, 2025). "In prostate cancer, Abiraterone inhibits androgen biosynthesis, whereas Enzalutamide blocks androgen receptor activity." (PMID 40277781, 2025). "Following extensive treatment with androgen receptor (AR) pathway inhibitors, advanced prostate cancer (PCa) frequently develops treatment resistance." (PMID 40691407, 2025). "The androgen receptor (AR) signaling pathway plays a pivotal role in the development and progression of prostate cancer, including advanced forms such as castration-resistance prostate cancer (CRPC)." (PMID 41020902, 2025). "After treatment with androgen receptor inhibitors, prostate cancer cells can switch to AR-independent growth and survival pathways." (PMID 41304766, 2025). "Meanwhile, related work has established that in some metastatic castration resistant prostate cancer patients, long-term AR inhibitors treatment creates a selective pressure to generate AR-independent tumors with an altered profile." (PMID 40017595, 2025). "These technologies allow for the selective degradation of dysregulated NRs, offering potential treatments for hormone-driven cancers like ER-positive breast cancer, AR-driven prostate cancer, and metabolic diseases such as T2DM." (PMID 40926269, 2025). "Notwithstanding, prostate cancer can engage diverse mechanisms to activate the androgen receptor (AR), resulting in the formation of AR-androgen complexes which can be translocated into cells and modulate gene expression." (PMID 40017595, 2025). "There has been a proliferation of novel treatments for the management of advanced prostate cancer (PCa), including androgen receptor pathway inhibitors (ARPI)." (PMID 40277797, 2025). "Further research has established a strong correlation between GPR75 and androgen receptor (AR) expression in prostate cancer (PCa) samples." (PMID 40362321, 2025). "It is postulated that prostate cancer progression is also mediated through OPNc, which activates androgen receptor signalling." (PMID 39941741, 2025). "This study shows that p300/CBP-dependent H2B acetylation is crucial for maintaining transcription of oncogenic gene programs in androgen receptor-driven prostate cancer." (PMID 41044247, 2025). "Longitudinal prostate cancer studies have characterized AR signaling changes during androgen deprivation therapy, elucidating key resistance mechanisms." (PMID 40940870, 2025). "In fact, direct stimulation of IL-1R on prostate cancer cells suppresses AR expression, thus potentially instigating further secretion of this cytokine in the surrounding tumor-associated stroma." (PMID 39858071, 2025).
prostate carcinoma (continued). "Regarding anti-androgenic mechanisms of action, numerous studies showed that resveratrol and other monomeric stilbenes exert antiproliferative and pro-apoptotic effects in prostate cancer by inhibiting the expression or hindering the function of AR." (PMID 40077738, 2025). "Taken together, our work presented here suggests the necessity of NKX3.1 in promoting growth of prostate cancer cells, even while AR is inhibited." (PMID 39858088, 2025). "While CRPC often retains reliance on AR signaling, approximately 20–30% of these resistant tumors represent androgen-indifferent prostate cancer (AIPC)." (PMID 39859392, 2025). "Reducing androgen levels or blocking androgen receptors (AR) can inhibit the progression of prostate cancer, making androgen deprivation therapy (ADT) a first-line treatment to prevent the progression and metastasis of prostate cancer." (PMID 40764425, 2025). "Even under castrate levels of circulating androgens, sustained AR activation supports progression toward castration-resistant prostate cancer, mirroring resistance mechanisms observed with AR overexpression and intratumoral steroidogenesis." (PMID 41375042, 2025). "In research published in Nature Cell Biology, the authors demonstrated that EZH2 plays a central role in driving lineage plasticity in prostate cancer, promoting neuroendocrine trans differentiation following androgen receptor (AR) inhibition." (PMID 40722714, 2025). "While AR is highly expressed in luminal epithelial cells and the prostate stroma, their respective contributions to prostate cancer etiology remain elusive." (PMID 41468516, 2025). "Our findings further demonstrate that AR signaling negatively regulates this axis, disrupting enhancer-promoter interactions and impairing ferroptosis sensitivity in prostate cancer cells." (PMID 40082405, 2025). "Mutations or overexpression of enzymes in androgen metabolic pathways enable prostate cancer cells to synthesize androgens independently, thus bypassing the need for exogenous androgens and activating the AR pathway, which leads to resistance." (PMID 41079787, 2025). "When looking at prostate cancer preclinical models, AR-negative and AR-low cell lines had higher survivin expression compared with AR-positive lines." (PMID 41304997, 2025). "Androgen receptor (AR) interact with multiple signaling pathways to promote the occurrence and progression of prostate cancer." (PMID 40503765, 2025). "AR supports proper development in normal prostate, whereas elevated AR expression drives disease progression in prostate cancer." (PMID 39917165, 2025). "The androgen receptor and androgen signaling are critical in almost all aspects of prostate cancer and allow us to focus model development on the most relevant molecular elements to the disease." (PMID 40840524, 2025). "The pathogenesis of prostate cancer is mainly driven by androgen receptor (AR) activation and aberrant nuclear factor kappa B (NF-κB) signaling, and the interaction between both pathways enhances tumor aggressiveness and therapeutic resistance." (PMID 40126263, 2025). "AR signaling inhibitors have improved overall survival for men with advanced prostate cancer, but treatment resistance is inevitable and includes reactivation of AR signaling." (PMID 39787247, 2025). "Prostate cancer is dependent on androgen receptor signalling and aberrations of the PI3K-Akt-mTORC1 pathway mediating excessive and sustained growth signalling." (PMID 39941741, 2025). "To develop potential anti-prostate cancer agents, in this study, we identified a novel ether-type arylpiperazine derivative as a potent androgen receptor (AR) antagonist, uncovering a series of effective antiproliferative compounds." (PMID 40224223, 2025).
prostate carcinoma (continued). "We found that Galectin-1 is upregulated in enzalutamide-resistant prostate cancer cells and promotes resistance by regulating androgen receptor expression." (PMID 39941722, 2025). "In prostate cancer, MALAT1 expression showed a strong association with AR positivity (90%), particularly in advanced and castration-resistant tumors." (PMID 40674376, 2025). "Recent studies have identified alterations in the Hippo-YAP signaling pathway within prostate cancer, highlighting intricate crosstalk with the AR signaling pathway." (PMID 39963114, 2025). "For example, ASR-600, a UA analog, effectively inhibited AR and AR-V7 signaling in prostate cancer cells." (PMID 40568370, 2025). "In prostate cancer, CAFs support tumor progression and modulate the microenvironment partly via androgen receptor signaling, highlighting their importance as key stromal regulators contributing to tumor growth and therapy resistance." (PMID 41179298, 2025). "In contrast, deleting FABP5 generated similar consequences as deleting the androgen receptor (AR) in prostate cancer cells, a major driver of the disease progression." (PMID 41374926, 2025). "We were specifically interested in discovering NR transcription factors in PDAC, similar to what is observed between FOXA1 and ESR1 in breast cancer and between FOXA1 and AR in prostate cancer." (PMID 41168397, 2025). "To define the potential mechanisms of AR-independent prostate cancer, we conducted single-cell transcriptomic profiling of human prostate cancers pre- and post-ADT." (PMID 39743630, 2025). "While functional studies in AR-positive LNCaP prostate cancer cells indicated that the hormone-dependent 5′-tRNA halves, but not the 3′-tRNA halves, promote cell proliferation, the underlying mechanism for this remained elusive." (PMID 40471969, 2025). "Several studies have shown that the AR is overexpressed in some human malignancies, such as prostate cancer, breast cancer, hepatocellular carcinoma, and bladder cancer." (PMID 41153666, 2025). "The role of AR signaling and androgens in metastatic prostate cancer is well understood, demonstrating that prostate cancer cells are highly adaptive at sustaining functional AR signaling to promote cancer growth." (PMID 40356745, 2025). "In summary, ARD1's role in prostate cancer is intertwined through multiple mechanisms, including the acetylation and nuclear translocation of AR and its interaction with ADAM9." (PMID 40026288, 2025). "Regarding advanced forms of PCa, even castration-resistant ones, the significant effects of BETis have been attributed to AR activity and signaling, with initial preclinical studies finding them less effective in AR-null versus AR-positive prostate cancer." (PMID 40407591, 2025). "The AR-YAP interaction exhibits distinct androgen dependency in different types of prostate cancer cells." (PMID 39963114, 2025). "First, blocking HSP90 function in prostate cancer decreases AR nuclear translocation and enhances its degradation, leading to decreased transcriptional activity and proliferation." (PMID 39787247, 2025). "ADT aims to suppress the production of androgens or inhibit androgen receptor signaling, thereby limiting the growth and survival of androgen‐dependent prostate cancer cells." (PMID 40955046, 2025). "This regulation of AR stability leads to reduced AR activity, which is a key driver of prostate cancer." (PMID 40432836, 2025). "In prostate cancer, Jag1-ICD has been shown to upregulate the expression of androgen receptor variants (AR-Vs) and to enhance AR transactivation under both androgen-dependent and -independent conditions." (PMID 41294868, 2025). "The androgen receptor (AR) is a central driving force in the incidence and progression of prostate cancer." (PMID 40008000, 2025). "Analogous mechanisms have also been proposed to account for the tumor suppressor function of YAP in ERα+ breast cancer and AR+ prostate cancer." (PMID 38979373, 2025).